CRP (C-reactive protein)
Diseases named in the same sentence as CRP in open-access papers (continued):
Sharing a sentence is not in itself a finding about the gene and the disease.
Hypertension (continued). "Increased serum levels of CRP, monocyte TNF-α secretion, and serum IL-6 concentrations were reported in patients with hypertension, suggesting a close association between inflammation and hypertension." (PMID 33937238, 2021). "Results of a cross-sectional sample of the Irish population showed enhanced diet quality assessed by Dietary Approaches to Stop Hypertension (DASH) was associated with a more favorable lipoprotein profile, BMI, WC, waist to hip ratio, and CRP." (PMID 33691729, 2021). "Our study found that the relationship between CRP and hypertension was attenuated after controlling for WC and BMI." (PMID 34925916, 2021). "Of 269 patients, 68 patients deceased within 12 months; therefore, the following 7 variables were chosen for the model: age, coronary artery disease, arterial hypertension, EF, creatinine, CRP and DNase activity." (PMID 34101826, 2021). "Patients receiving LPV/r or DRV/c were more likely younger, men, had higher C-reactive protein but less likely had hypertension, ischemic heart or chronic pulmonary or severe kidney disease." (PMID 34179035, 2021). "In the subgroup of hypertension, the survival rate was significantly lower in patients with increased CRP, LDH, and D‐dimer, or decreased lymphocytes." (PMID 33112011, 2021). "In the multivariate model, sex, age, hypertension, renin-angiotensin-aldosterone system inhibitor use, haematocrit, creatinine, D‐dimer, CRP and Charlson Comorbidity Index were taken into account, in addition to cardiac injury." (PMID 33860908, 2021). "Based on feature selections and regression analysis, predictors of in-hospital mortality in SCAD patients include elevated c-reactive protein, atrial fibrillation, hypertension, and steroid use." (PMID 33903608, 2021). "Compared with participants in the highest category of total PA, participants in the lowest category also had a higher BMI, smoked more, drank slightly more alcohol, were diagnosed with hypertension, and had higher levels of C-reactive protein and HbA1c." (PMID 33434193, 2021). "Other variables included in the multivariate model were hypertension, ferritin, d-dimer and c-reactive protein." (PMID 34113503, 2021). "Statin use was associated with a reduced risk of COPD exacerbation, and statins have also been shown to independently lower CRP and reduce cardiovascular events related to hypertension." (PMID 34537026, 2021). "We recruited 342 women with incident hypertension from rural Senegal, and measured C-reactive protein (CRP) and malondialdehyde (MDA) in DBS and concurrent blood pressure (BP) at baseline and 1-year follow-up." (PMID 34943129, 2021). "Patients receiving LPV/r or DRV/c were more likely younger, men, had higher C-reactive protein levels while less likely had hypertension, cardiovascular, pulmonary or kidney disease." (PMID 34179035, 2021). "The inflammation marker considered to be significantly correlated with hypertension is CRP, and it has been confirmed that prehypertensive and hypertensive patients have elevated levels of CRP in blood serum." (PMID 34868060, 2021). "The risk for possible sarcopenia was significantly greater among individuals with hypertension, or high concentration of CRP in rural populations(p<0.001)." (PMID 33661964, 2021). "Based on our previous findings, we a priori selected five parameters: CRP, hypertension status, age, and neutrophil and lymphocyte counts (CHANeL)." (PMID 34158545, 2021). "A multivariate model was performed with an automatic logistic regression by back steps, including IP-10 > 173.35 pg/mL together with age, hypertension, creatinine, lymphocyte counts, D Dimer and CRP as adjusting variables." (PMID 34357148, 2021). "Participants in the lowest category of total PA smoked more, had higher body mass index and C-reactive protein, and were diagnosed with hypertension." (PMID 33434193, 2021).
Hypertension (continued). "After adjusting for gender, age, hemoglobin, complement C3, CRP, hypertension, diabetes, coronary artery disease, cerebral infarction, and immunoglobulin G, ln(IDO) was still an independent risk factor for ACR (OR = 2.7, p < 0.05)." (PMID 33506062, 2021). "CRP is an acute protein whose concentration in serum reflects the inflammation of patients and is related to cardiovascular diseases, such as AS, hypertension, myocardial infarction." (PMID 34288824, 2021). "Only a small proportion of studies involved other proxy measures for CVD outcomes, such as C-reactive protein, flow-mediated dilation, or hypertension." (PMID 34501699, 2021). "This prognostic role of the first chest CT appears to be stronger than that of age, sex, BMI, hs-CRP, hypertension, and pre-renal azotemia." (PMID 33788067, 2021). "Mesothelin was additionally affected by bronchitis, elevated C-reactive protein and current hypertension." (PMID 34768395, 2021). "Ctrees were able to exclude OA and CPPD as possible differentials based on elevated uric acid, C-reactive protein (CRP), presence of arterial hypertension, and sex, diagnosing gout with a sensitivity and specificity of 95.1% and 41.6%, respectively." (PMID 34063875, 2021). "Clinically, higher levels of C-reactive protein (a common marker of systemic inflammation) or IL-6 (an inflammatory cytokine released along with CRP) strongly predict future development of hypertension." (PMID 35155614, 2021). "OSA-induced hypoxic stress and oxidative stress increase circulating inflammatory mediators, including adhesion molecules, inflammatory cytokines and C-reactive protein, leading to hypertension and cardiovascular events." (PMID 33879148, 2021). "The associations of hypertension and HDL-C with physiological successful aging over six years stratified by important variables (baseline age, CRP, and IL-6)." (PMID 34847175, 2021). "Even if, chefs often had higher CRP-concentration (40.0%), office workers suffered more from hypertension (37.5%)." (PMID 34068356, 2021). "Univariate logistic regression analysis found that age, hypertension, fever (39°C ≤ T), total bilirubin, CRP, lymphocytes, blood glucose, and bilateral pneumonia were related to severe cases." (PMID 34710058, 2021). "All models based on CHANeL (age, hypertension, serial CRP, and neutrophil and lymphocyte counts during the first 3 days of hospitalization) showed high accuracy." (PMID 34158545, 2021). "Logistic regression, logistic LASSO regression, Random Forest, Support Vector Machine, and XGBoost analyses were performed based on age, hypertension status, serial CRP, and neutrophil and lymphocyte counts during the first 3 days of hospitalization." (PMID 34158545, 2021). "A number of previous observational studies reported associations between indicators of inflammation, such as C-reactive protein, interleukin-6, interleukin-8, WBC count, neutrophil count, neutrophil to lymphocyte ratio, and incidence of hypertension." (PMID 33529192, 2021). "We have carried out formal mediation analyses to investigate the extent to which the effect of body mass index (BMI) on COVID‐19 severity is mediated by glycaemia, LDH, CRP and hypertension." (PMID 33851033, 2021). "The Odds ratio (OR) remained unchanged for sTNFRI (1.72, p=0.00001), sTNFRII (1.45, p=0.0027), sIL2Rα (1.40, p=0.0023), IGFBP6 (1.51, p=0.0032) and CRP (1.47, p=0.0046) after adjusting for confounding variables, HbA1C, hypertension and dyslipidemia." (PMID 33868296, 2021). "The prevalence of hypertension was higher in women with elevated CRP (33.9% vs. 15.8%, p < 0.0001) and in women with elevated AGP, albeit without statistical significance (30.9% vs. 18.2%, p = 0.08)." (PMID 34103653, 2021). "Multivariate logistic regression analysis was done for the pre-terminal event CRP, pre-terminal event ferritin, lactic acid, age, and hypertension." (PMID 34868744, 2021).
Hypertension (continued). "First, elevated c-reactive protein, atrial fibrillation, hypertension and steroid use are important predictors of SCAD mortality." (PMID 33903608, 2021). "Nevertheless, Yanget al. declared that patients with hypertension came with highly detected inflammatory markers such as CRP (p=0.024), Procalcitonin (p=0.017) and IL6 (p=0.017)." (PMID 34912542, 2021). "A trend relationship between the serum levels of hs-CRP and incident hypertension was observed (p< 0.001)." (PMID 34925916, 2021). "Treatment with metformin decreases retinal leukocyte adhesion 204, palmitic acid-induced monocyte adhesion 205, and reduces clinically relevant high levels of CRP-induced ED and hypertension." (PMID 34646376, 2021). "The results showed that the hs-CRP groups were significantly and positively correlated with the incidence of hypertension (p < 0.05)." (PMID 34925916, 2021). "Women were older (mean age 67 vs. 62 years in men, p = 0.003), and they had a higher prevalence of arterial hypertension, lower hemoglobin, creatinine and CRP, and higher lymphocyte counts." (PMID 33142963, 2020). "In this study, the comparison between the two groups showed differences in gender, history of hypertension, dyspnea symptom, creatinine, and C-reactive protein levels." (PMID 32493370, 2020). "In univariate analysis the risk factors for developing AF in the acute phase of infarction were: female sex, age, hypertension, smoking HR on Holter, CRP > 3 mg/L, eGFR, log-NTproBNP, chronic use of ARB/ACE inhibitors and chronic use of beta-blockers." (PMID 32423138, 2020). "Compared to stable mild group (n = 69), patients in the progression group (n = 16) were more likely to be older, male, presented with dyspnea, with hypertension, and with higher levels of lactase dehydrogenase and c-reactive protein." (PMID 32493370, 2020). "In the present study, baseline hs-CRP and IL-1β levels in the hypertension group were significantly higher than those in the control group (normal BP at both baseline and follow-up), whereas baseline IL-6 levels showed an increasing trend." (PMID 32292598, 2020). "C-reactive protein (CRP), interleukin (IL) 6, and tumour necrosis factor alpha (TNF-α) relate positively to hypertension, and risk prediction models that include CRP have been developed." (PMID 33392493, 2020). "A few studies have also demonstrated a relationship between hypertension and inflammatory biomarkers (e.g. C-reactive protein, D-dimer and interleukin-6), immune activation and microbial translocation." (PMID 32487185, 2020). "The same study reported that miR-155 levels are inversely associated with proatherogenic metabolic risk factors (age, hypertension, total cholesterol, and HDL-C, LDL-C, and CRP levels) and the severity of atherosclerotic lesions." (PMID 33339419, 2020). "Other factors associated with kidney function decline included female, uncontrolled hypertension, elevated CRP, and baseline eGFR." (PMID 33083456, 2020). "Prevalence of hypertension was 14.58% (7 cases) and 39.29% (11 cases) in the CRP 1 group and CRP 2 group, respectively." (PMID 32414383, 2020). "Low-grade inflammation in terms of elevated CRP and higher WBC or monocyte counts impairs vascular function, causing higher vascular stiffness, which is associated with a higher risk of hypertension." (PMID 32397256, 2020). "Individuals with incident type 2 diabetes were older and had higher BMI, waist circumference, TG, ALT, AST, GGT, and CRP levels and hypertension prevalence." (PMID 33302966, 2020). "According to the univariate logistic regression analyses, GNRI < 92, male sex, presence of hypertension, ischemic etiology, use of diuretics, low serum potassium and hemoglobin levels, elevated CRP levels, and increased BNP levels showed p-values < 0.15." (PMID 32325805, 2020).
Hypertension (continued). "HbA1c induces dyslipidemia, hyperhomocysteinemia, and hypertension and increases C-reactive protein, oxidative stress, and blood viscosity, which would contribute to the development of cardiovascular diseases." (PMID 32190696, 2020). "This is in line with our observation showing that patients with higher CRP concentrations had a higher proportion of comorbid conditions, such as hypertension and higher body-mass index." (PMID 32993521, 2020). "Age, sex, hypertension, preoperative hematocrit, eGFR, serum albumin and C-reactive protein level, intraoperative MAP, C.I. and SvO2 reduction below each cut-off of ROC analysis were considered as covariables." (PMID 33189145, 2020). "Hypertension, lymphopenia and high blood levels of markers of inflammation (including CRP) are among these reported RFs." (PMID 32864192, 2020). "Further, KLF2 expression in humans is inversely associated with numerous inflammatory and metabolic disease metrics, such as TNFA expression, soluble C-reactive protein levels, body mass index (BMI), and hypertension." (PMID 33208733, 2020). "Increases in serum hs-CRP level increase the risk of CVD by 2–5 times, diabetes mellitus, hypertension, depression and cancer." (PMID 31814938, 2019). "It was also suggested that there was a remarkable correlation between CRP and incident hypertension after the normalization of other biomarkers." (PMID 31340788, 2019). "Considering the clinical data, the presence of DM, systemic hypertension, dyspnea, thoracic pain, temperature levels and CRP levels were significantly different between the groups." (PMID 31718571, 2019). "Key metabolic determinants in the progression to CVD, including hypertension, elevated hs-CRP, and central obesity, as well as type 2 diabetes, were prevalent." (PMID 31469876, 2019). "C-reactive protein (CRP), a plasma marker that indicates inflammation, has been proposed to link with an elevated risk of hypertension." (PMID 31048753, 2019). "Age, body mass index (BMI), hypertension as well as albuminemia, CRP and KT/V showed a difference between groups according to the vaccine response." (PMID 33708291, 2019). "The values of serum resistin, C- reactive protein and total leukocyte count were found significantly raised in patients of hypertension, angina pectoris and myocardial infarction with hypertension as compared to normal participants (p<0.001 for all)." (PMID 31258568, 2019). "Some circulating biomarkers, such as C-reactive protein (CRP), plasminogen activator inhibitor-1, and aldosterone, have been associated with incident hypertension, but results have been conflicting." (PMID 31581667, 2019). "The clinical data are sparse for hypertension, cholesterol levels and CRP, but one experimental study has demonstrated that GDF8 deletion in a mouse model of metabolic syndrome resulted in increased muscle mass and prevented an increase in blood pressure." (PMID 31906236, 2019). "Hypertension is associated with higher levels of TNF α, IL6, IL1β, IL17, and C Reactive Protein (CRP)." (PMID 31921123, 2019). "Covariates including CRP and family history of hypertension accounted for 75.8% of the variation in DBP response to MODERATE." (PMID 30706700, 2019). "Hypertension, hyperlipidemia, CIMT, CRP, and insulin resistance are all well-known CVD risk factors." (PMID 31385484, 2019). "The high fructose-enriched diet induced cardiometabolic disorders (hypertension, hyperglycemia, IR and dyslipidemia), an increase in uric acid concentration, transaminase activities and C-reactive protein level." (PMID 31835800, 2019). "Serum levels of resistin, C-reactive protein and total leucocyte count are significantly raised with increasing inflammatory pathogenesis of the cardiovascular disease in patients of hypertension and coronary artery disease as compared to normal subjects." (PMID 31258568, 2019).
Hypertension (continued). "Our objective was to compare the levels of serum resistin, C-reactive protein and total leucocyte count in subjects of hypertension and coronary artery disease; and to observe the correlation of serum resistin with CRP and TLC in the study participants." (PMID 31258568, 2019). "The acute phase protein, C-reactive protein (CRP), is an inflammatory marker strongly associated with hypertension." (PMID 31412635, 2019). "In a prospective study that examined the risk factors for CVD in participants to the Scottish Health Surveys who were followed over 7 years, the greatest risk of CVD was observed in participants with FH‐CVD and elevated CRP or hypertension." (PMID 31175686, 2019). "In the present study, the CRP level was significantly associated with MetS, especially several components such as central obesity, low HDL, and hypertension." (PMID 31752150, 2019). "The final modified Framingham scoring (MFS) model consisted of anemia, high-sensitivity C-reactive protein, left ventricular ejection fraction, and five Framingham factors (age, sex, total and high-density lipoprotein cholesterol, and hypertension)." (PMID 29338684, 2018). "Increased C-reactive protein is observed in half of Turner syndrome patients, which results in a chronic inflammatory state in the vascular endothelium and can likely lead to hypertension due to endothelial dysfunction." (PMID 29747617, 2018). "The link between CRP and CSU and a higher risk of arterial hypertension was demonstrated considering only older patients probably due to a higher prevalence of hypertension in this phase of life." (PMID 30584542, 2018). "Indeed, CRP values were positively associated with pregnancy adverse outcomes both in the univariate (β=0.043, 95% CI 0.003-0.083, p=0.036) and in the multivariate model when maternal age, hypertension, and development of GDM were considered (β=0.05, 95% CI 0.010-0.090, p=0.015)." (PMID 30533423, 2018). "First, the differences in NK cell percentage between the two groups are associated with the cardiovascular characteristics of participants, such as hypertension status, hs-CRP levels, male, hyperglycemia, and being overweight." (PMID 29662662, 2018). "In this multivariate analysis model, eGFR is independently associated with circulating levels of MCP-1 (P < 0.001), sVCAM-1 (P < 0.0001), hs-CRP (P < 0.01), and hypertension (P < 0.01)." (PMID 30301260, 2018). "Risk of development of atherosclerosis can be predicted from the disease risk factors and/or inflammatory markers such as hyperlipidemia, hypertension, hyperglycemia, and high C-reactive protein (CRP)." (PMID 30400262, 2018). "Women experiencing MAO were older, more frequently suffering from hypertension, and showed higher CRP concentrations, with a cutoff value >1.86 μg/mL found by a ROC curve analysis to be accurately predictive for MAO." (PMID 30533423, 2018). "Our findings are in agreement with previous studies showing that higher levels of CRP are related to hypertension and pulse pressure." (PMID 29101422, 2018). "There is now convincing evidence that NAFLD is tightly linked to the cardiometabolic risk factors studied here, i.e. glucose dysregulation, dyslipidemia, hypertension and elevated CRP." (PMID 30133541, 2018). "The causal relationship between recurrence of atrialfibrillation and factors such as left atrial diameter, C-reactive protein,hypertension, left ventricular ejection fraction, chronic obstructivepulmonary disease, and body mass index was determined." (PMID 30652742, 2018). "The levels of CRP alter on a daily basis and increase with age, high blood pressure, smoking, smokeless tobacco use, and alcohol consumption." (PMID 30842796, 2018). "The results of numerous studies have shown a clear connection between hypertension and relatively elevated CRP levels." (PMID 28326006, 2017).